REG4 (regenerating family member 4)
Diseases named in the same sentence as REG4 in open-access papers (continued):
Sharing a sentence is not in itself a finding about the gene and the disease.
colorectal cancer (continued). "Given the interplay between Reg4 and colorectal cancer aggressiveness, we sought to investigate if expression of Reg4 and its downstream proteins are associated with clinical recurrence and overall survival in stage II and III colorectal cancer patients treated with curative intent." (PMID 33659040, 2021). "REG4 promotes colorectal cancer cell division through Akt/GSK-3β/β-catenin/TCF-4 pathway." (PMID 33489872, 2020). "REG4 was upregulated in colorectal cancer tissues than in adjacent normal mucosa, indicating that REG4 overexpression may be an early event in colorectal carcinogenesis." (PMID 33489872, 2020). "Colorectal cancer patients with high tumor content of REG4 exhibit a poorer overall survival rate and disease-free survival rates compared to patients with tumors devoid of REG4." (PMID 31696115, 2019). "The marked increase in REG4 mRNA (regenerating islet-derived family member 4, 87-fold) in SSA/Ps, is of interest because it is increased in gastric and colorectal cancers and is associated with resistance of cancer cells to chemotherapy and radiation induced cell death." (PMID 24533081, 2014). "Association of REG4 expression with other biomarkers in colorectal cancer and non-mucinous colorectal cancer." (PMID 25295732, 2014). "Taken together, these findings suggested that REG4 is a potent activator of the EGFR/Akt pathway for the proliferation and anti-apoptosis of colorectal cancer cells." (PMID 36172286, 2022). "We performed in vitro experiments using HT29 and SW480 colorectal cancer cell lines using these peptides to interfere with endogenous CD44ICD and to block Reg4-mediated effects." (PMID 33659040, 2021). "The use of REG4 antagonists or Akt inhibitors decreased, while GSK-3β antagonist significantly increased mitotic index and proliferation in colorectal cancer cells." (PMID 33489872, 2020). "Consequently, the Reg4-mediated activation of TCF4 results in the upregulation of cyclin D1 and D3 and their partners CDK4 and CDK6 enhancing the proliferation of human colorectal cancer cells." (PMID 31696115, 2019). "Furthermore, Reg4 expression in non-mucinous colorectal cancer served as an independent marker of favorable prognosis, which was completely contrary to our understanding of its tumor-promoting activity." (PMID 39857608, 2024). "REG4 expression was less frequently observed in colorectal cancer than in adjacent non-neoplastic mucosa, in well- and moderately-differentiated adenomas than in mucinous carcinoma, and in the cancers of the right colon than in the left colon and rectum, respectively." (PMID 36172286, 2022). "Additionally, colorectal cancer patients with metastatic recurrence in the liver showed more frequent REG4 immunostaining and serum levels than in those without recurrence." (PMID 33489872, 2020). "REG4 expression indicates higher overall survival rates in non-mucinous colorectal cancer patients." (PMID 33489872, 2020).
colon cancer (16 papers, 2012 to 2025). "Although its biological function remains poorly understood, REG4 is reported to be a potent activator of the EGFR/Akt/AP-1 signaling pathway in colon cancer cells and closely linked with the inhibition of apoptosis." (PMID 26077911, 2015). "Recently, knockout of Reg4 in mice suppressed colon cancer stem cell markers and in a patient cohort, Reg4 was significantly associated with CRC stem cell markers." (PMID 33659040, 2021). "Reg4 acts as a growth factor with exogenous Reg4 stimulating growth and in vitro invasiveness of colon cancer cells." (PMID 33659040, 2021). "Cooperation between the GATA6/LGR5 and GATA6/REG4 pathways plays an important role in the tumorigenicity in colon cancer cells." (PMID 33489872, 2020). "In the present study, we identified REG4 as a novel target gene of GATA6 and showed that GATA6-mediated activation of REG4 expression is essential for the growth of colon cancer cells under adherent conditions in culture and their tumorigenicity in vivo." (PMID 26387746, 2015). "Studies in colon cancer cell lines showed that REG4 expression was enhanced by stimulation with transforming growth factor (TGF)α, EGF, bFGF and HGF, and in hepatocellular carcinoma cell lines by stimulation with TGF-β." (PMID 26077911, 2015). "Our findings suggest that GATA6 simultaneously induces the expression of genes essential for colon cancer cell growth under adherent conditions (REG4) and genes that promote their clonogenicity (LGR5)." (PMID 26387746, 2015). "We subsequently examined the expression levels of GATA6 protein and REG4 mRNA in colon cancer cell lines by immunoblotting and qRT-PCR analyses, respectively." (PMID 26387746, 2015). "Among the markedly increased genes in SSA/Ps that have also been reported to be increased in colon cancer were REG4, AQP5, MUC2, TFF1, KLK10." (PMID 24533081, 2014). "In a colon cancer model, REG4 was induced by growth factors, including transforming growth factor-alpha, epidermal growth factor (EGF), basic fibroblast growth factor and hepatocyte growth factor." (PMID 23342005, 2013). "MicroRNA (miR)-363 suppressed the translation of GATA binding protein 6 (GATA6), which functioned as a transcriptional factor to induce REG4 and leucine-rich repeat-containing G-protein coupled receptor 5 (Lgr5) expression essential for the growth of colon cancer cells under adherent conditions." (PMID 36172286, 2022). "In fact, REG4 knockdown induces apoptosis and inhibits the proliferation of colon cancer cells." (PMID 31696115, 2019). "Furthermore, we demonstrated that the addition of recombinant REG4 to the culture medium partially restores the proliferation of colon cancer cells expressing miR-363 or those in which GATA6 was knocked down." (PMID 26387746, 2015). "Furthermore, we demonstrate that GATA6-mediated induction of REG4 enhances the growth of colon cancer cells under adherent conditions." (PMID 26387746, 2015). "Moreover, we show that GATA6-mediated activation of REG4 enhances the growth of colon cancer cells under adherent conditions and is required for their tumorigenicity." (PMID 26387746, 2015). "However, no significant negative correlation was detected between miR-363 and LGR5 or REG4 expression ratios (Tumor/Normal) in clinical samples and colon cancer cell lines." (PMID 26387746, 2015). "REG4 operates downstream the transcription factor GATA6 and has shown potent mitogenic and pro-metastatic effects in gastric and colon cancers." (PMID 39632825, 2024). "It would therefore be intriguing to assess the role of the GATA6/REG4 and GATA6/LGR5 pathways in the properties of colon cancer stem cells." (PMID 26387746, 2015). "Thus, miR-363 may repress the growth of colon cancer cells via inhibition of REG4 expression." (PMID 26387746, 2015). "To investigate the significance of REG4 in the tumorigenesis of colon cancer, we generated HT29 cells expressing a lentiviral shRNA targeting REG4 and injected these subcutaneously into nude mice." (PMID 26387746, 2015).
colon cancer (continued). "MicroRNA-363, which is reduced in colon tumors, suppresses GATA6 leading to REG4 downregulation." (PMID 31696115, 2019). "28, 29, REG4 expression was found to be elevated in colon tumor tissues compared with the surrounding non-tumor tissues." (PMID 26387746, 2015). "28, 29, 32, we found that REG4 and LGR5 expression was elevated in many colon tumors." (PMID 26387746, 2015). "In conclusion, our findings demonstrate that GATA6 simultaneously induces the expression of genes essential for the growth (REG4) and clonogenicity (LGR5), and that cooperation between the GATA6/REG4 and GATA6/LGR5 pathways is important for the tumorigenicity of colon cancer cells." (PMID 26387746, 2015). "REG4 protein also transactivates EGFR signaling and reduces apoptosis in colon cancer cells." (PMID 24533081, 2014). "Thus, reduced miR-363 expression in colon cancer cells may contribute to the upregulation of GATA6 and consequently of REG4." (PMID 26387746, 2015). "Thus, REG4 and LGR5 may contribute independently to the tumorigenicity of colon cancer cells." (PMID 26387746, 2015).
pancreatic cancer (16 papers, 2009 to 2025). "REG4 overexpression was associated with poor prognosis and resistance to gemcitabine treatment in one study, suggesting that adjuvant therapies that target reg4 could enhance the usual gemcitabine-based treatment of pancreatic cancer." (PMID 38203561, 2023). "It is worth noting that although Reg4 plays a certain role in pancreatic regeneration, it also plays an important role in the occurrence, development, and invasion of pancreatic cancer as a serum marker of cancer." (PMID 38915894, 2024). "The pancreatic cancer patients with a higher serum REG4 concentration had an unfavorable response to RCT and frequently experienced local recurrence after surgery." (PMID 36172286, 2022). "The regenerating gene family member 4 (REG4), a small, secreted lectin-like protein, is expressed at a higher level in pancreatic cancer tissues than in adjacent normal tissues." (PMID 35742884, 2022). "Previous studies show that pancreatic cancer-derived factor REG4 promotes cultured macrophage to a M2 phenotype and stimulates cancer cell proliferation in vitro." (PMID 35742884, 2022). "The REG4 secreted by pancreatic cancer cells promoted macrophage polarization to M2 via EGFR/Akt/cAMP-responsive element binding activation, finally promoting tumor growth and distant metastasis." (PMID 36172286, 2022). "The knockdown of REG4 or an anti-REG4 antibody both attenuated the cell viability of pancreatic cancer cells, while rhREG4 exposure showed the opposite effect in a dose-dependent manner." (PMID 36172286, 2022). "In pancreatic tumors, REG4 mRNA expression was significantly higher in intestinal-type rather than in gastric-type intraductal papillary mucinous neoplasms and normal pancreatic ductal epithelium." (PMID 36172286, 2022). "REG4 expression, which is increased in pancreatic cancer cells compared with normal pancreatic cells, can promote the invasiveness and proliferation of tumor cells." (PMID 34577861, 2021). "Analyzed IHC biomarkers that can differentiate pancreatic cancer from chronic pancreatitis encompass REG4, POSTN, CA242, Galectin-1, maspin, pVHL, IMP3, CD13, and PAM4." (PMID 34988027, 2021). "REG4 is overexpressed in pancreatic cancer tissues than in adjacent normal tissues at either the mRNA or protein level." (PMID 33489872, 2020). "It was previously shown that forced reg4 overexpression in vitro increases cell growth rate and resistance to programmed cell death in non-pancreatic cancer-derived cells." (PMID 19834624, 2009). "The first observation was that pancreatic cancer-derived cells overexpressing REG4 protein grew more rapidly and were more resistant to gemcitabine treatment." (PMID 19834624, 2009). "In this paper we report that the reg4 gene, positioned on chromosome 1p13.1-p12, is present in increased copy number in pancreatic cancer cells and in late precancerous pancreatic lesions." (PMID 19834624, 2009). "The relationship betweena gain in reg4 gene copy number and cancer development was investigated on the human pancreatic cancer cell line Mia-PaCa2 xenografted under the skin of nude mice." (PMID 19834624, 2009). "Studies on a xenografted pancreatic cancer cell line showed that reg4 over-expression stimulates tumor growth and, conversely, that blocking circulating reg4 protein with a specific antibody inhibits tumor growth." (PMID 19834624, 2009). "Altogether, these results suggest that overexpression of the REG4 protein, induced by its early gain in gene copy number, plays a major role in pancreatic tumor development and resistance to anticancer drugs." (PMID 19834624, 2009). "The overexpression of REG4 is related to enhanced pancreatic cancer growth." (PMID 35742884, 2022). "The current review study identifies 22 IHC biomarkers as diagnostic tools for pancreatic cancer that embrace: Pentraxin-3, ENO1, REG4, POSTN, CA125, CA242, Galectin-1, Galectin-9, Maspin, pVHL, MUC1, MUC5AC, THBS2, LTBP2, CPA4, IMP3, CD13, Dkk1, KOC, S100P, Mesothelin, PAM4." (PMID 34988027, 2021).
pancreatic cancer (continued). "Moreover, gliotactin (GLI), a transcription factor in the hedgehog signaling pathway, was also identified to bond to REG4 promoter region and induce REG4 expression in pancreatic cancer." (PMID 33489872, 2020). "Conversely, treatment with recombinant REG4 enhanced cell growth in a dose-dependent manner, indicating that targeting REG4 may be a potential targeted therapy in pancreatic cancer." (PMID 33489872, 2020). "Serum REG4 levels could be correlated with REG4 expression in cancer tissues, and they were elevated in patients with pancreatic cancer than in healthy individuals and those with chronic pancreatitis." (PMID 33489872, 2020). "In addition, an increased copy number of this region was also found in almost all PanIN3, the latest stage of precancerous pancreatic lesions, suggesting that reg4 gene amplification is an early event in pancreatic cancer development." (PMID 19834624, 2009). "The early amplification of its gene in pancreatic cancer described in this study and its oncogenic activity reported in the literature prompted us to further study the role of REG4 in pancreatic tumorigenicity and in resistance of pancreatic cancer to gemcitabine treatment." (PMID 19834624, 2009). "Because the limited efficiency of pancreatic cancer treatment with gemcitabine might be due to the presence of stroma in tumors, we looked whether reg4 overexpression influenced the extent of stroma formation in subcutaneously xenografted Mia-PaCa2 cells." (PMID 19834624, 2009). "This is to our knowledge the first report of reg4 gene copy number gain in pancreatic cancer." (PMID 19834624, 2009). "It was concluded that adjuvant therapies targeting reg4 could improve the standard treatment of pancreatic cancer with gemcitabine." (PMID 19834624, 2009). "Altogether, these results indicate that targeting reg4 protein might be used in cooperation with gemcitabine to treat pancreatic cancer." (PMID 19834624, 2009). "In the context of primary pancreatic cancer, TFF1 was the marker for low ARS score, and REG4 is the marker for high ARS score." (PMID 40612666, 2024). "In the gastrointestinal tract, REG4 expression was found to have increased in inflammatory bowel diseases (IBD), as well as in colorectal, gastric, and pancreatic cancer." (PMID 34577861, 2021). "The key transcriptional factor in the Hedgehog signaling pathway, GLI family zinc finger 1 (GLI1) bound to REG4 promoter regions (GATCATCCA) for its transcription and translation in pancreatic cancer cells, supported by the synergic expression of REG4 and GLI1." (PMID 36172286, 2022).
colitis (11 papers, 2011 to 2025). Inflammation of the colon. "Notably, tumours express Notum and Reg4, that have been documented as markers of Wnt pathway activation and colitis-associated-cancer, respectively." (PMID 40386410, 2025). "REG family proteins are activated in colitis, and REG4 has been proved as a target for intestinal epithelial stem cell enrichment and mucosal healing." (PMID 38426148, 2024). "Reg4 knockout (KO) mice were highly sensitive to DSS-mediated colitis, whereas human REG4 intestine epithelial cell transgenic (huREG4IECtg) mice exhibited more resistance to DSS-mediated colitis." (PMID 39636005, 2024). "Data showed that Reg4 KO mice were more sensitive to DSS-mediated colitis, whereas huREG4IECtg mice exhibited significantly stronger resistance as compared to the littermate controls." (PMID 39636005, 2024). "We next employed feces transplanted mouse model to investigate whether feces transplantation could affect the DSS-mediated colitis in Reg4 KO or huREG4IECtg mice." (PMID 39636005, 2024). "We also found that cis-9 CLA gavage could promote the resistance of Reg4 KO mice to the DSS-mediated colitis." (PMID 39636005, 2024). "We further examined whether IL-35 determined the sensitivity of mice to DSS-mediated colitis in Reg4 KO mice using recombinant mouse (rm) IL-35 and huREG4IECtg mice using IL-35 neutralizing antibodies." (PMID 39636005, 2024). "Interestingly, feces transplantation from wild-type (WT) to Reg4 KO mice could reduce the sensitivity to DSS-mediated colitis; whereas the feces transplantation from WT to huREG4IECtg mice could increase the sensitivity to DSS-mediated colitis." (PMID 39636005, 2024). "In contrast to the Reg4 KO mice, huREG4IECtg mice showed markedly resistance to DSS-mediated colitis." (PMID 39636005, 2024). "To investigate the roles of REG4/Reg4 in gut immune homeostasis, we employed a mouse model of dextran sodium sulfate (DSS)-mediated colitis." (PMID 39636005, 2024). "The dominant E. coli were isolated from colitis tissues of mice and found to be sensitive to both CFD- and Reg4-mediated attack complexes." (PMID 32879431, 2020). "The VNN1 finding, together with increased REG4 and MUC17, that are also increased during colitis, suggests that the development of SSA/Ps may at least in part involve inflammatory processes." (PMID 24533081, 2014).